INS (insulin)
Diseases named in the same sentence as INS in open-access papers (continued):
Sharing a sentence is not in itself a finding about the gene and the disease.
gestational diabetes (continued). "In all 4 cases, BGL was checked in the asymptomatic infants as their mothers had been diagnosed with gestational diabetes which had not required insulin treatment." (PMID 36398453, 2023). "Hence, although OGTT and MMTT responses were described using the same model to estimate insulin sensitivity, our method remains to be validated in a broader population, including patients with manifested T2DM and gestational diabetes." (PMID 37892445, 2023). "In addition, gestational diabetes mellitus (GDM), a condition in which hormones from the placenta block the body from successfully utilizing insulin, is more likely to develop in pregnant women who are physically inactive." (PMID 37681809, 2023). "Plasma GLP-1 concentrations in the third trimester of pregnancy are strongly predictive of insulin concentrations (and indices of insulin secretion and resistance) but not of glucose concentrations or the presence of gestational diabetes." (PMID 37439859, 2023). "While there is no specific treatment for gestational diabetes mellitus, it is often managed using lifestyle interventions like controlled diets and exercise to improve insulin sensitivity in pregnant mothers." (PMID 36381747, 2022). "Maternal characteristics, lipid profiles and glucose metabolism and insulin indices in the first and second trimesters in women with and without gestational diabetes mellitus." (PMID 36714591, 2022). "Among nulliparous women, 17% were diagnosed with gestational diabetes without insulin treatment required, as opposed to 22% among multiparous women." (PMID 36591332, 2022). "Carbohydrate-restricted dietary (CRD) pattern for gestational diabetes mellitus (GDM) has been widely used in clinics, but the change in insulin utilization rate beyond CRD intervention in GDM remains unclear." (PMID 35057540, 2022). "Lastly, because differences in the rate of gestational diabetes were not expected, specific tests of insulin secretion and insulin sensitivity were not conducted." (PMID 33626041, 2021). "One ethanolic SCOPA extract has been shown to have beneficial effects on adipose tissue function, hepatic lipid accumulation, and insulin sensitivity in a mouse model of DIO, and a different extract was found to attenuate gestational diabetes in a small human study." (PMID 35211087, 2021). "Gestational diabetes mellitus (GDM) is glucose intolerance first recognised in pregnancy and is managed by providing dietary and lifestyle advice, together with pharmacological support, such as oral hypoglycaemics and/or insulin when needed." (PMID 34072685, 2021). "Gestational diabetes mellitus occurs either when the pancreas does not produce enough insulin or when the insulin it produces cannot be used efficiently by the body." (PMID 33880369, 2021). "Patients with Type 2 or gestational diabetes can produce some insulin, but not enough to properly regulate blood glucose levels in the context of insulin resistance." (PMID 33633812, 2021). "Using the same STELA approach, we more recently reported shorter telomeres in male placenta from pregnancies where mothers were diagnosed with gestational diabetes, but not medically treated with metformin or insulin." (PMID 34299077, 2021). "Due to these increasing set of evidence, inositols have been studied in women in the context of a variety of conditions where defective insulin function and excessive body mass index are present, such as PCOS, gestational diabetes and menopausal-related weight gain." (PMID 33859622, 2021). "In the UK, NICE guidelines suggest considering glyburide only for women with gestational diabetes who do not respond to or cannot tolerate metformin but decline insulin." (PMID 32442232, 2020). "We found that the threshold risk of development of gestational diabetes requiring insulin (GDM-2) occurred at lower BMI values (26.9 kg/m2), compared to gestational diabetes without insulin (29.1 kg/m2)." (PMID 32599847, 2020).
gestational diabetes (continued). "In Morocco, only insulin is currently approved as treatment for women whose gestational diabetes is not sufficiently controlled by diet alone." (PMID 32448233, 2020). "The mother once again developed gestational diabetes but did not require insulin treatment unlike the previous pregnancy." (PMID 31989990, 2020). "We were unable to measure serum insulin and glucose levels, but it was clear from the medical history that all of participants were routinely screened for gestational diabetes mellitus (GDM), and there were no complications during pregnancy." (PMID 32635165, 2020). "In this cohort, there were temporal, but not seasonal, increases in gestational diabetes incidence between the years 2001 and 2009, which appeared to be related more to reductions in insulin secretion than sensitivity." (PMID 31087162, 2019). "Jane L. Tarry-Adkins and colleagues report that neonates whose mothers were treated for gestational diabetes with metformin as opposed to insulin weigh less at birth but have a higher BMI by mid-childhood." (PMID 31386659, 2019). "However, reduced β-cell reserve or their maladaptation to higher insulin demands may result in gestational diabetes mellitus (GDM)." (PMID 30469427, 2018). "The majority of patients with gestational diabetes did not return postpartum to perform OGTT and in our study the only factor implicated in a higher postpartum return was the use of insulin during pregnancy." (PMID 29308091, 2018). "Furthermore, irisin correlates positively with fat mass, BMI, fasting insulin, and HOMA-IR in women with gestational diabetes." (PMID 28658348, 2017). "Another recent study reported a negative relation between the onset of gestational diabetes mellitus (GDM) and β cell loss by using the detection of unmethylated INS DNA." (PMID 28450972, 2017). "Both, gestational diabetes mellitus (GDM) and pre-gestational diabetes mellitus (PGDM) have been demonstrated to contribute to changes in the expression and activity of glucose transporters in the placenta, with insulin therapy as a possible modulatory factor." (PMID 27981520, 2017). "Metformin is effective and safe in gestational diabetes mellitus (GDM) and could be used instead of insulin in such cases." (PMID 27597988, 2016). "Since data that would answer this question are scare, the aim of this study was to compare validated parameters of insulin sensitivity and secretion between pGDM with NGT five years after gestational diabetes and healthy controls (five years after normal pregnancy)." (PMID 25873951, 2015). "When pancreatic function is not sufficient to overcome the insulin resistance, gestational diabetes develops." (PMID 26473833, 2015). "Young women, born small as a consequence of their mothers' undernutrition during pregnancy, may have difficulty in coping with the insulin resistance and metabolic demands of pregnancy, resulting in hyperglycemia and higher rates of gestational diabetes mellitus (GDM)." (PMID 26798340, 2015). "The different forms of DM include type 1 (insulin-dependent), type 2 (non-insulin-dependent) and gestational diabetes." (PMID 25574214, 2015). "In a study of pregnant women with and without gestational diabetes, serum CX3CL1 levels were similar between groups, but independently associated with HOMA-IR, suggesting effects on insulin signaling." (PMID 26393344, 2015). "Women with previous gestational diabetes mellitus (pGDM) and postpartum normal glucose tolerance (NGT) may carry impaired islet β cell secretion, insulin resistance and subsequent altered glucose homeostasis." (PMID 26405461, 2015). "In another study, DNA methylation levels at the maternally imprinted MEST gene were significantly lower in placenta and cord blood of women with gestational diabetes (88 treated dietetically and 98 with insulin) than in those without gestational diabetes." (PMID 24664798, 2014).
gestational diabetes (continued). "Five participants were not included at delivery owing to the development of insulin-treated gestational diabetes mellitus." (PMID 23835065, 2013). "In conclusion, this retrospective multicenter study demonstrates that pregnancy outcome in women with type 2 and gestational diabetes mellitus treated with insulin lispro protamine suspension was similar to those of those treated with NPH insulin, except for a lower insulin requirement." (PMID 23840206, 2013). "Although they found that grand multipara had a higher rate of insulindependent gestational diabetes, after doing conditional logistic regression, it was not an independent predictor of insulin-dependent gestational diabetes mellitus." (PMID 22737503, 2011). "In addition, GCF-EVs were increased in both gestational diabetes mellitus (GDM) and periodontitis, and their proteomic cargos included peptides of both host and bacterial origin that participated in immune–inflammatory responses, glucose metabolism, and insulin signaling." (PMID 41153802, 2025). "We believe that systemic immune-inflammation index and lymphocyte–monocyte ratio values measured in the first-trimester complete blood count parameters are effective in predicting gestational diabetes mellitus but are not effective in determining insulin requirement." (PMID 39356958, 2024). "SMTNL1 also acts as an insulin-sensitizing agent by increasing the gene expression of PP2A and DUPS9 protein phosphatases, resulting in decreased ERK1/2 activity and, hence, decreasing the phosphorylation of IRS-1 at Ser612 under gestational diabetes conditions." (PMID 38883605, 2024). "However, when insulin production does not compensate for placental hormones’ impact, gestational diabetes ensues." (PMID 39203767, 2024). "Interestingly enough, for a long time, the only non-experimental treatment used for gestational diabetes besides lifestyle changes was insulin." (PMID 37296725, 2023). "Given the harms that result from untreated gestational diabetes, in situations where alternative treatments such as insulin are not feasible, metformin may be extremely useful to achieve maternal normoglycaemia and thus mitigate these risks." (PMID 37670017, 2023). "This may have been influenced by the nature of our sample — most participants presented with mild or moderate gestational diabetes, 93.0% of whose condition was controlled with diet and oral hypoglycemic agents rather than insulin treatment." (PMID 36451171, 2022). "We also included pregnant women with GDM who were not on insulin therapy, as any existing treatment for gestational diabetes could interfere with synbiotic efficacy or affect the composition of gut microbiota." (PMID 35729675, 2022). "The objects of study were patients with pregestational diabetes mellitus (PGDM) and 62 patients with GDM who were diagnosed by oral glucose tolerance test (OGTT) and insulin release test from February 2017 to February 2019." (PMID 35936373, 2022). "Gestational Diabetes Mellitus (GDM): GDM (gestational diabetes mellitus) is a situation that may arise during pregnancy, in which the placenta produces a hormone that hinders the body from adequately utilizing insulin." (PMID 35546393, 2022). "Studies in knock-out mice suggest that the regulatory subunits may have negative effects on insulin action, with increased expression of p85α also observed in mouse models of gestational diabetes and in obese humans." (PMID 35157107, 2022). "However, it must be noted that none of the mothers had developed gestational diabetes, or even clinically elevated fasting glucose or insulin levels, nor were any of the infants born large for gestational age." (PMID 34061777, 2021). "Lactogens signal through the PRLR to stimulate pancreatic β-cell proliferation and insulin levels in vitro and in vivo, and the specific deletion of the PRLR in pancreatic tissue and in β-cells leads to failure to expand β-cell mass during pregnancy and to gestational diabetes." (PMID 33746901, 2021).
gestational diabetes (continued). "In the Metformin in Gestational Diabetes: The Offspring Follow Up (MiG: TOFU) study, at two years of age, metformin-exposed offspring demonstrated higher subcutaneous adiposity and larger mid-upper arm circumferences and bicep and subscapular skinfolds than insulin-exposed offspring." (PMID 34071182, 2021). "However, some pregnant women are not able to intensify insulin secretion thus developing Gestational Diabetes Mellitus (GDM)." (PMID 33504861, 2021). "In human studies, circulating Fetuin-B levels were elevated in obese individuals, patients with gestational diabetes mellitus (GDM) and T2DM, and related to IR and insulin secretion." (PMID 33061822, 2020). "However, the pregnancy process was a physiological insulin resistance state, but not all pregnant women had gestational diabetes, and some returned to normal after delivery." (PMID 33083291, 2020). "Gestational diabetes mellitus (GDM) is defined as glucose intolerance of variable degree, with onset or first recognition during pregnancy, whether insulin or only diet modification is used for treatment and whether or not the condition persists after giving birth." (PMID 34466559, 2020). "Impaired postprandial glucose, insulin, and glucagon-like peptide-1 (GLP-1) responses have been reported in gestational diabetes mellitus (GDM) patients." (PMID 31921879, 2019). "Furthermore, in pregnant women circulating kisspeptin levels significantly correlated with insulin responses to oral glucose challenge and were significantly lower in women with gestational diabetes (GDM) compared with those without GDM." (PMID 31619585, 2019). "The American Congress of Obstetricians and Gynecologists (ACOG) Practice Bulletin #30 in 2001 recommended adding insulin if glycemic control could not be achieved with nutritional therapy alone for women with gestational diabetes." (PMID 31775682, 2019). "These discrepancies can be attributed to the possibility of good glycemic control of women with gestational diabetes in these studies through good obstetric monitoring, balanced diet and insulin treatment, factors which have not been specifically assessed in our study." (PMID 30231873, 2018). "Furthermore, DIO dams had normal blood glucose and serum insulin levels in our study, suggesting the absence of gestational diabetes mellitus despite the obese phenotype." (PMID 28588000, 2017). "Indeed, gestational diabetes mellitus exposed neonates had higher umbilical cord blood insulin levels than not exposed neonates, which was confirmed by the ANN analysis." (PMID 27440187, 2016). "However, UCB leptin levels did not correlate with UCB insulin levels in the offspring of obese women with gestational diabetes mellitus." (PMID 27440187, 2016). "Since no data exist on CTX and osteopontin in gestational diabetes, we aimed to investigate their plasma concentrations as well as their relations to insulin sensitivity and insulin secretion in women with gestational diabetes and women with normal glucose tolerance during pregnancy and postpartum." (PMID 22844418, 2012). "Gestational diabetes (GD) is defined as carbohydrate intolerance of varying degrees of severity with onset or first recognition during pregnancy, regardless of whether insulin is used for treatment or the condition persists after pregnancy." (PMID 20416099, 2010). "In women with a suboptimal beta-cell function, the increase in insulin secretion may not be sufficient to compensate the increased insulin resistance, resulting in gestational diabetes mellitus (GDM)." (PMID 19123930, 2009). "In gestational diabetes mellitus (GDM), the maternal β-cells can no longer adequately adapt to the increased food supply and insulin demands during late pregnancy." (PMID 38791525, 2024). "Gestational diabetes mellitus (GDM) is a condition that develops during pregnancy when the body does not produce sufficient insulin to manage elevated blood sugar levels." (PMID 39777075, 2024).
gestational diabetes (continued). "Inositol supplementation (in the form of myo-Ins and D-chiro-inositol) is currently used as an effective alternative to the classic insulin-sensitizing molecule, metformin, in many gynecological and endocrinological diseases, such as PCOS, gestational diabetes mellitus (GDM) and male infertility." (PMID 39199391, 2024). "Moreover, plasma ADM concentrations are higher in pregnant women with gestational diabetes mellitus (GDM), and ADM inhibits β-cell insulin production and secretion in vitro." (PMID 36180668, 2023). "Among pregnant women who contracted COVID-19 in the second trimester, 19.4% experienced gestational diabetes mellitus (GDM) without the need for insulin therapy (p = 0.01)." (PMID 37762087, 2023). "Furthermore, about two in ten women had gestational diabetes without insulin." (PMID 36591332, 2022). "Our purpose is to study the evolution of mitochondrially derived peptides (MDPs) and their relationship with changes in insulin sensitivity from the early stages of pregnancy in a cohort of pregnant women with and without gestational diabetes (GDM)." (PMID 35683389, 2022). "Pathologies of pregnancy, such as preeclampsia (PE) and gestational diabetes mellitus (GDM), and abnormal maternal conditions, such as pregestational maternal obesity (PGMO) and maternal obesity in pregnancy, show with reduced insulin signalling in the foetoplacental vasculature." (PMID 29104874, 2017). "In addition, whether or not insulin sensitivity is influenced by breastfeeding during the first year postpartum in women with recent gestational diabetes, independent of obesity and weight changes during the postpartum period, is unclear." (PMID 28725256, 2017). "A low GI diet can also reduce the need for insulin use for women with gestational diabetes mellitus (GDM) without compromise of fetal outcomes." (PMID 23201846, 2012). "The administration of probiotics does not influence the incidence of gestational diabetes, with the only recorded action being a minimal decrease in FPG by increasing insulin sensitivity." (PMID 40362845, 2025). "Gestational diabetes mellitus (GDM) is a rising problem which, if not diagnosed and treated in time, can lead to maternal, fetal, and neonatal complications, and even children born to diabetic mothers will be more resistant to insulin in childhood." (PMID 40766851, 2025). "Material and Methods: The study population comprised 70 participants, including mothers with gestational diabetes who were treated with a diet and physical activity (GDM G1), with insulin (GDM G2), and a control group of healthy mothers without gestational diabetes (non-GDM)." (PMID 39599657, 2024). "Gestational Diabetes Mellitus (GDM) is defined as any degree of glucose intolerance which is diagnosed for the first time during pregnancy, irrespective of treatment with diet or insulin." (PMID 37582776, 2023). "Although the role of miR-106a-5p in gestational diabetes has never been investigated, there is evidence of its implication in glucose homeostasis as it targets FOXO1, a key regulator of insulin signaling." (PMID 37298229, 2023). "CPAP treatment in women with gestational diabetes and OSA improved insulin secretion but not glucose levels." (PMID 37762913, 2023). "IR increases during pregnancy, and if the insulin secretion from the pancreatic β-cells is not able to compensate, hyperglycaemia and eventually gestational diabetes (GDM) may ensue." (PMID 35323652, 2022). "In addition, a study on gestational diabetes mellitus showed that the phosphatidylinositol-3-kinase and protein kinase B pathway could be repressed by regulating FLOT2 expression, suggesting FLOT2 inhibition could alleviate insulin resistance and liver gluconeogenesis." (PMID 35692841, 2022).